ATP1A1 (ATPase Na+/K+ transporting subunit alpha 1)
Description:
Catalytic subunit of the Na(+)/K(+)-ATPase pump that hydrolyzes ATP to exchange ions across the plasma membrane, exporting 3 Na(+) and importing 2 K(+) per cycle against electrochemical gradients. It undergoes ATP-driven conformational changes that allow alternating binding and release of Na(+) and K(+) ions across the membrane. This process maintains essential Na(+) and K(+) gradients for membrane potential and cellular function. Could also be part of an osmosensory signaling pathway that senses body-fluid sodium levels and controls salt intake behavior as well as voluntary water intake to regulate sodium homeostasis (By similarity).
Synonyms: CMT2DD; HOMGSMR2
Tractability: Small molecule: an approved drug acts on it; a structure with a bound ligand is known; a high-quality ligand is known; it belongs to a druggable protein family. Antibody: UniProt places it where antibodies can reach, with high confidence; its Gene Ontology location is reachable by antibodies, with high confidence; UniProt predicts a signal peptide or a membrane-spanning region; the Human Protein Atlas places it where antibodies can reach. PROTAC: ubiquitination databases record sites on it; its protein half-life has been measured; a small molecule that binds it is known.
Target class: P-type ATPase; Sodium potassium ATPase; Primary active transporter; Transporter
Safety:
Unwanted effects reported when the protein is acted on. In parentheses: how it was acted on, where the effect was seen, and who reports it.
atrioventricular block (inhibition, acute dosing; renal, cardiovascular; source: Lynch et al. (2017))
cardiac arrhythmia (inhibition, acute dosing; renal, cardiovascular; source: Lynch et al. (2017))
decreased heart rate (inhibition, acute dosing; renal, cardiovascular; source: Lynch et al. (2017))
increased cardiac contractility (inhibition, acute dosing; renal, cardiovascular; source: Lynch et al. (2017))
increased urinary sodium excretion (inhibition, acute dosing; renal, cardiovascular; source: Lynch et al. (2017))
increased urine excretion (inhibition, acute dosing; renal, cardiovascular; source: Lynch et al. (2017))
ventricular fibrillation (inhibition, acute dosing; renal, cardiovascular; source: Lynch et al. (2017))
vomiting (inhibition, acute dosing; renal, cardiovascular; source: Lynch et al. (2017))
Gene: Protein-coding gene on chromosome 1 (116,372,668 to 116,410,261, forward strand). Ensembl gene ENSG00000163399.
Subcellular location: Cell membrane; Basolateral cell membrane; Cell membrane, sarcolemma; Cell projection, axon; Melanosome
Subcellular location (Human Protein Atlas): Plasma membrane; Vesicles
Pathways (Reactome):
Disease: Potential therapeutics for SARS
Muscle contraction: Ion homeostasis
Transport of small molecules: Ion transport by P-type ATPases
Gene Ontology:
Molecular function: ATP hydrolysis activity; P-type sodium:potassium-exchanging transporter activity; protein binding; protein-folding chaperone binding; steroid hormone binding; ATP binding; potassium ion binding; sodium ion binding; nucleotide binding; P-type potassium transmembrane transporter activity; phosphatase activity; transmembrane transporter binding
Biological process: cellular response to steroid hormone stimulus; intracellular potassium ion homeostasis; intracellular sodium ion homeostasis; membrane repolarization; potassium ion import across plasma membrane; potassium ion transmembrane transport; response to glycoside; sodium ion export across plasma membrane; sodium ion transmembrane transport; cardiac muscle cell action potential involved in contraction; cell communication by electrical coupling involved in cardiac conduction; establishment or maintenance of transmembrane electrochemical gradient; membrane repolarization during cardiac muscle cell action potential; proton transmembrane transport; regulation of sodium ion transport; relaxation of cardiac muscle; osmosensory signaling pathway; potassium ion transport; sodium ion homeostasis
Cellular component: apical plasma membrane; extracellular exosome; extracellular vesicle; lateral plasma membrane; lysosomal membrane; melanosome; organelle membrane; plasma membrane; protein-containing complex; sodium:potassium-exchanging ATPase complex; sperm flagellum; T-tubule; basolateral plasma membrane; endoplasmic reticulum; Golgi apparatus; membrane; membrane raft; photoreceptor inner segment membrane; sarcolemma; axon; postsynaptic density
Genetic constraint (gnomAD): Loss-of-function variants: 14 observed, 116.15 expected, observed/expected ratio (o/e) 0.12, 90% interval 0.079 to 0.19. The upper end of that interval is the gene's LOEUF score, 0.19, which puts it in group 1 of 6, group 1 being the genes least tolerant of losing a copy. Missense variants: 523 observed, 1,352.9 expected, observed/expected ratio (o/e) 0.39, 90% interval 0.36 to 0.42. Synonymous variants: 471 observed, 489.46 expected, observed/expected ratio (o/e) 0.96, 90% interval 0.89 to 1.04.
Gene-disease validity (ClinGen):
ClinGen rates the evidence that ATP1A1 causes each of these diseases.
Charcot-Marie-tooth disease, axonal, type 2DD (autosomal dominant): Moderate.
Cancer hallmarks: escaping programmed cell death (promotes); invasion and metastasis (promotes)
Homologues: Orthologues: chimpanzee ATP1A1 (99% identical), macaque ATP1A1 (99% identical), pig ATP1A1 (99% identical), mouse Atp1a1 (97% identical), guinea pig ATP1A1 (97% identical), rat Atp1a1 (96% identical), dog ATP1A1 (95% identical), tropical clawed frog atp1a1 (91% identical), rabbit ATP1A1 (91% identical), zebrafish atp1a1a.1 (89% identical), zebrafish atp1a1b (88% identical), zebrafish atp1a1a.4 (88% identical), and 7 more. Paralogues in human: ATP1A2 (87% identical), ATP1A3 (86% identical), ATP1A4 (78% identical), ATP12A (65% identical), ATP4A (63% identical), ATP2A1 (30% identical), ATP2A2 (30% identical), ATP2B2 (30% identical), ATP2B3 (29% identical), ATP2B1 (29% identical), ATP2B4 (28% identical), ATP2A3 (28% identical), and 9 more.
Diseases named in the same sentence as ATP1A1 in open-access papers:
ATP1A1 is named in the same sentence as 130 diseases in open-access papers, as found by Europe PMC text mining. Sharing a sentence is not in itself a finding about the gene and the disease. The quoted sentences say what the papers report.
adenoma (17 papers, 2015 to 2025). A neoplasm arising from the epithelium. "The mutations of ATP1A1 (such as p.Leu104Arg) are also predominantly found in adenomas with cells resembling the ZG (i.e., in ZG-like APAs), as are the ATP2B3 aldosterone-driving mutations." (PMID 40725432, 2025). "Several lines of evidence suggest that KCNJ5-mutant aldosterone-producing adenomas have distinct clinicopathological phenotype compared to those harboring ATP1A1, ATP2B3, and CACNA1D mutations." (PMID 29594118, 2018). "Somatic variants of ATP1A1 were reported to cause aldosterone producing adenomas in primary aldosteronism." (PMID 27701467, 2016). "Furthermore, somatic mutations in other genes, such as KCNJ5, CACNA1D, and ATP1A1, have been implicated in aldosterone-producing adenomas, highlighting the complex genetic landscape of adrenal tumors." (PMID 41007858, 2025). "The observed pathological variants of aldosterone-producing adenomas in our cohort were KCNJ5 (N=5), ATP1A1 (N=5), and CACNA1D (N=4) mutations." (PMID 39897961, 2024). "Several somatic mutations have been found in aldosterone-producing adenomas in KCNJ5, ATP1A1, ATP2B3, CACNA1D, and CTNNB1 genes." (PMID 32783015, 2020). "Adenomas with CTNNB1 mutations showed a large number of differentially expressed genes (1360 compared to 106 and 75 for KCNJ5 and ATP1A1/ATP2B3 respectively) and clustered together in a hierarchical clustering analysis." (PMID 31000732, 2019). "At the molecular level, somatic mutations involving potassium channels (KCNJ5), ATPases (ATP1A1 and ATP2B3), and calcium channels (CACNA1D) account for approximately 60% of sporadic aldosterone-producing adenomas." (PMID 29594118, 2018). "Targeted sequencing for the reported mutations in APAs of KCNJ5, CACNA1D, ATP1A1, ATP2B3 and CTNNB1 exons was performed from the adenomas." (PMID 28102204, 2017). "In the last decade, somatic pathogenic variants in KCNJ5, CACNA1D, ATP1A1 and ATP2B3 genes, which are involved in maintaining intracellular ionic homeostasis and cell membrane potential, were described in aldosterone-producing adenomas (aldosteronomas)." (PMID 35813615, 2022). "Leak currents have been described previously in reports of ATP1A1 mutations in nonexcitable adenoma cells and in a study of ATP1A1 mutations diagnosed in two patients with epilepsy." (PMID 34717959, 2021). "In particular, ATP1A1 and CACNA1D mutations have been found in men with small adenomas." (PMID 33912136, 2021). "Moreover, we have used Sanger sequencing to confirm that there were no other conventional and well-characterized aldosterone-driving gene mutations, including KCNJ5, ATP1A1, CACNA1D, and CTNNB1, in the adenoma harboring with ATP2B3 K416_F418delinsN mutation." (PMID 34572956, 2021). "In contrast, tumors that are composed predominantly of ZG-like compact cells are typically enriched in ATP1A1-, ATP2B3-, and CACNA1D-mutant aldosterone-producing adenomas that show increased and strong CYP11B2 expression and predominantly negative CYP11B1 or CYP17A1 expression profiles." (PMID 29594118, 2018).
hepatocellular carcinoma (13 papers, 2012 to 2025). A malignant tumor that arises from hepatocytes. "Similarly, ATP1A1, another protein identified in our dataset, has been associated with fibrotic progression by promoting cell migration and proliferation, particularly in hepatocellular carcinoma." (PMID 41036229, 2025). "Several solid tumors, like sarcomas, prostate, breast, pancreatic, lung, colorectal, and liver carcinomas, show ATP1A1/BCL2L1 levels below the average in the TCGA pan-cancer analysis." (PMID 37904054, 2024). "The effect of 5 on anti-proliferation and downregulation of ATP1A1 expression in another hepatoma cell line (Huh-7) was also preliminarily verified by experiments." (PMID 36985801, 2023). "The down-regulation of ATP1A1 expression can inhibit the apoptosis and migration of hepatocellular carcinoma." (PMID 36985801, 2023). "Knockdown of ATP1A1 decreased proliferation, migration, and tumorigenicity in hepatocellular carcinoma and squamous cell carcinoma." (PMID 35618735, 2022). "The overexpression of α1 subunit of Na+/K+-ATPase (ATP1A1) were observed in esophageal squamous cell carcinoma, non-small-cell lung cancer and hepatocellular carcinoma, contributing to cancer proliferation and migration." (PMID 34350460, 2021). "Overexpression of ATP1A1 has been reported in tumor specimens from patients with medulloblastoma, glioblastoma, melanoma, hepatomas, and non-small-cell lung cancer." (PMID 27845894, 2016). "Platinum accumulation defects mediated by decreased expression of ATP1A1 have been shown in H4-II-E/CDDP cisplatin resistant rat hepatoma cells." (PMID 22792399, 2012). "Research studies had showed that ATP1A1 could be a novel therapeutic target for hepatocellular carcinoma." (PMID 34690763, 2021). "In human hepatocellular carcinoma, ATP1A1 was known to promote carcinoma development." (PMID 28484360, 2017). "Clinically, the expression of ATP1A1 is higher in a large proportion of hepatocellular carcinoma (HCC) patients." (PMID 36985801, 2023). "In a clinical setting, ATP1A1 is highly expressed in a large proportion of hepatocellular carcinoma (HCC) patients." (PMID 36985801, 2023).
melanoma (12 papers, 2014 to 2025). A malignant, usually aggressive tumor composed of atypical, neoplastic melanocytes. "Thus, we aimed to investigate ATP1A1 expression in melanoma samples to determine its association with patient survival and response to targeted therapy." (PMID 38178183, 2024). "Bufalin disrupts the ATP1A1-Cav-1 complex, reversing drug resistance in melanoma, while cardiac glycosides inhibit STAT1-mediated IDO1 expression, demonstrating synergy with immune checkpoint inhibitors." (PMID 40821775, 2025). "In melanoma, ATP1A1 forms a complex with Cav-1 to activate Src/AKT signaling, promoting therapeutic resistance and T-cell suppression." (PMID 40821775, 2025). "The ATP1A1 isoform has been found to be overexpressed in various cancers, including melanoma, compared to healthy tissues." (PMID 38178183, 2024). "To further validate the involvement of ATP1A1 in resistance to BRAF-targeted therapy, we conducted experiments using three different models of melanoma cell lines (harbouring mutations in cKIT, BRAF or NRAS)." (PMID 38178183, 2024). "It is known that the α1 subunit of the Na,K-ATPase (ATP1A1) is overexpressed in non-small-cell lung cancer, renal clear cell carcinoma, glioblastoma, melanoma and, as shown here, colon cancer." (PMID 38713004, 2024). "To assess the subcellular localization of ATP1A1 in melanoma cells, we conducted immunofluorescence and confocal microscopy analyses." (PMID 38178183, 2024). "Alternatively, potentially targetable cancer types emerge (i.e., Ewing’s sarcoma and melanoma showing the highest ATP1A1/BCL2L1 levels)." (PMID 37904054, 2024). "We aimed to assess ATP1A1 prognostic value in melanoma patients and examine the impact of its ligand, bufalin, on melanoma cell lines in vitro and in vivo." (PMID 38178183, 2024). "Firstly, we analyzed a TCGA (The Cancer Genome Atlas) dataset using The Human Protein Atlas and identified that ATP1A1 mRNA is significantly overexpressed in melanoma compared to 16 other cancer types." (PMID 38178183, 2024). "For example, a combination of conventional anti-cancer drugs effectively prevented relapses in a TNBC xenograft model, and an MAP kinase inhibitor and CGs synergistically induced cell death by targeting ATP1A1 in a mouse melanoma model." (PMID 38730618, 2024). "In vitro, bufalin induced apoptosis in melanoma cell lines by acting on ATP1A1 (siRNA experiments) and, in vivo, significantly impeded melanoma growth using a nude mouse xenograft model with continuous bufalin delivery via an osmotic pump." (PMID 38178183, 2024). "From a mechanistic point of view, our knock-down experiments and disruption of caveolae validated ATP1A1 in caveolae as the main target of bufalin in melanoma." (PMID 38178183, 2024). "Then, we assessed the impact of bufalin, one of the natural ligands of ATP1A1, on sensitive and resistant melanoma cell lines both in vitro and in vivo." (PMID 38178183, 2024). "Given the significant role of ATP1A1 in melanoma progression and resistance to targeted therapy, we investigated the impact of bufalin, a ligand of ATP1A1, on cell proliferation using crystal violet assays." (PMID 38178183, 2024). "As observed, ATP1A1 was highly expressed in Ewing’s-sarcoma, melanoma, and colorectal carcinoma, whereas ATP1A3 was highly expressed in neuroblastoma, Burkitt lymphoma, and T-lymphocytic leukemia." (PMID 32684846, 2020). "This indicated that ATP1A1 mRNA content negatively correlate with bufalin efficiency in melanoma cell lines (p = 0.047, Pearson correlation)." (PMID 32785105, 2020). "ATP1A1 expression is usually incresased in some types of cancers, such as lung cancer, liver cancer, glioblastoma and melanoma." (PMID 28484360, 2017). "Consistent with our results, immunohistochemistry data from the Human Protein Atlas showed normal skin has limited ATP1A1 expression, while 8 of 10 melanomas have ATP1A1 staining in >75% of cells." (PMID 27545456, 2016).
melanoma (continued). "We tested ATP1A1 protein levels by immunohistochemistry in normal human skin, benign nevi, primary melanoma and metastatic melanoma specimens." (PMID 27545456, 2016). "This reflects on-target inhibition of the ATP1A1 Na+/K+ pump, which is highly expressed by melanoma." (PMID 27545456, 2016). "In primary and metastatic melanomas, ATP1A1 staining was robust and nearly homogeneous among melanoma cells." (PMID 27545456, 2016). "Western analysis showed limited ATP1A1 expression in normal human melanocytes, but elevated expression in immortalized melanocytes and some xenografted melanomas." (PMID 27545456, 2016). "In support of this, two previous studies reported ATP1a1 to be present in melanosomes purified from melanoma and RPE cells." (PMID 25051489, 2014). "Based on our findings, ATP1A1 emerges as a promising target for melanoma treatment, and its inhibition by bufalin could be considered to reduce cancer progression by overcoming resistance to MAPK inhibitors." (PMID 38178183, 2024). "Furthermore, we investigated the expression of the ATP1A1 gene in 8 metastatic melanoma patients harbouring the V600EBRAF mutation, which is the most common mutation in melanoma." (PMID 38178183, 2024). "Additionally, through transcriptome profiling of 11 melanoma cell lines, we found the presence of ATP1A1 in the Verfaillie proliferative gene signature, which is associated with the melanocytic state characterized by MITF and SOX10 expression." (PMID 38178183, 2024). "The involvement of the ATP1A1-Cav1-Src complex in the inhibitory activity of cardiotonic steroids on signaling pathways has been demonstrated in various cancer types, and now we have established its significance in melanoma." (PMID 38178183, 2024). "Additionally, examining the RNA-seq database and transcriptome profiling of 11 melanoma cell lines established by the Bordet team, we discovered that ATP1A1 is part of the Verfaillie proliferative gene signature, which is associated with the melanocytic state." (PMID 38178183, 2024). "High ATP1A1 expression (IHC) correlated with reduced overall survival in melanoma patients." (PMID 38178183, 2024). "ATP1A1 reportedly is overexpressed in non-small cell lung cancer, melanomas, and glioblastomas." (PMID 31114755, 2019). "siRNA inhibition of ATP1A1 expression using 3 different siRNAs depleted A375 melanoma cells." (PMID 27545456, 2016). "However, we observed significantly higher ATP1A1 expression in all melanomas compared with normal human melanocytes." (PMID 27545456, 2016). "Cardiac glycosides thus kill melanoma cells by inhibiting ATP1A1." (PMID 27545456, 2016). "To test whether the prolonged survival of mice treated with digitoxin plus MEK inhibitor required inhibition of ATP1A1 we over-expressed mouse Atp1a1 in M481 melanoma cells (which is insensitive to therapeutic doses of cardiac glycosides)." (PMID 27545456, 2016). "Since our data were obtained from a small cohort, it will be necessary to confirm these findings with a larger population to establish whether ATP1A1 levels could be routinely evaluated to better define which melanoma patients would benefit from targeted therapy." (PMID 38178183, 2024). "Ectopic expression of mouse Atp1a1, but not human ATP1A1, blocked the effects of digitoxin on viability and plasma membrane depolarization in cultured melanoma cells from all three patients and A375 melanoma cells." (PMID 27545456, 2016).